CRP (C-reactive protein)
Diseases named in the same sentence as CRP in open-access papers (continued):
Sharing a sentence is not in itself a finding about the gene and the disease.
coronary artery disease (continued). "RDW was shown associated with inflammatory cytokine hs-CRP in patients with coronary artery disease." (PMID 29254274, 2017). "In a meta‐analysis of nearly 200 000 participants, the relative risk for coronary heart disease (CHD) was 1.00 (0.90 to 1.13) per 1 SD higher genetically raised CRP concentration." (PMID 28409825, 2017). "CRP has been shown to predict the risk of coronary heart disease (CHD) events in men and women independently of traditional risk factors." (PMID 28355230, 2017). "On the other hand, a huge randomization meta-analysis conducted by Wensley and colleagues showed that CRP levels genetically determined by CRP polymorphisms including rs1205 are unrelated to risk for coronary heart disease." (PMID 27386381, 2016). "A recent study of coronary artery disease patients has also showed an association of RDW with CRP, in which higher RDW was related to worse survival." (PMID 27906969, 2016). "If variants in the IL6R gene region were assumed to be instrumental variables for CRP, then the false conclusion would be reached that CRP was causal for coronary heart disease risk." (PMID 26291580, 2016). "Studies found a significant association between CRP level and subsequent coronary heart disease mortality in middle-aged men, women, and elderly people." (PMID 27434049, 2016). "An increase in CRP from less than 0.9 mg/l to above 2.4 mg/l has been associated with a doubled risk of developing coronary heart disease." (PMID 26875192, 2016). "Epidemiological studies have assessed the relationship between CRP concentration and n-3 fatty acid intakes in healthy subjects and in patients with coronary disease, confirming an inverse association and suggesting an anti-inflammatory effect of n-3 PUFAs." (PMID 27544079, 2016). "On the other hand, high CRP level has an association with the risks of coronary heart disease, ischemic stroke, and death from various cancers and lung disease." (PMID 25793462, 2015). "CRP concentration has continuous associations with the risk of coronary heart disease, ischemic stroke and vascular morality." (PMID 26114433, 2015). "Accordingly, elevated C-reactive protein (CRP), a marker reflecting the individual’s systemic inflammatory status, has been consistently associated with increased risk of coronary heart disease events and type 2 diabetes." (PMID 25962728, 2015). "It is also known to be associated with major adverse events in patients with coronary artery disease in a CRP independent manner." (PMID 25874928, 2015). "Nowadays, new risk factors such as lipoprotein A, fibrinogen, homocysteine, and inflammatory markers such as CRP (C-reactive protein) have posed themselves as the potential risk factors of coronary artery disease." (PMID 26170518, 2015). "The US Preventive Services Task Force performed a meta-analysis of 22 studies showing that CRP concentrations greater than 3.0 mg/L were associated with an approximate 60% excess risk of incident coronary heart disease as compared to levels less than 1 mg/L." (PMID 26378571, 2015). "In the EPIC-Norfolk Perspective Population Study, elevated blood levels of IL-8 in 785 healthy men and women predicted future coronary artery disease events after adjustment for traditional risk factors, C-reactive protein, and white cell count." (PMID 24995121, 2014). "We found significant SNPs in our analyses that have been previously reported to be associated with asthma, C-reactive protein levels (rs4129267), and coronary heart disease (rs2229238) in the NHGRI GWAS catalog." (PMID 25340798, 2014). "The target CRP SNP rs7553007 in these metastatic patients was analyzed because of its strong association with CRP levels, which was previously reported in coronary heart disease." (PMID 23755178, 2014). "The present study found an inverse linear association between CRP marker and cognitive performance in a sample of patients with ischemic heart disease." (PMID 24587705, 2014).
coronary artery disease (continued). "A CRP levels above 10 mg/L is associated with increased risk of several diseases including stroke, coronary heart disease, rheumatoid arthritis, hypertension, and colorectal cancer." (PMID 24516611, 2014). "The aim of this study was to analyse the association between changes in CIMT and hs-CRP values in cases with stable and unstable coronary artery disease." (PMID 24217304, 2013). "Patients with depression have increased platelet reactivity, decreased heart variability and increased inflammatory markers, such as C-reactive protein, which are all risk factors for coronary heart disease." (PMID 24171883, 2013). "White blood cell count (WBC) and C-reactive protein (CRP) are markers of inflammation that have been associated with an increased incident of coronary heart disease." (PMID 24083379, 2013). "Studies have demonstrated that high-sensitivity C-reactive protein (hs-CPR) is an independent risk factor of coronary heart disease and is closely related to the occurrence and development of the disease." (PMID 23596481, 2013). "Examples of genetic variants which have been used in this way for coronary heart disease include variants in the CRP gene for the causal effect of C-reactive protein, and variants in the IL6R gene for the causal effect of interleukin-6 receptor." (PMID 24062299, 2013). "C-reactive protein (CRP) is proposed as a screening test for predicting risk and guiding preventive approaches in coronary artery disease (CAD)." (PMID 23579782, 2013). "High concentrations of CRP were present in atheromatous plaques and have been implicated in the propagation of coronary artery disease." (PMID 24363620, 2013). "Some studies have shown that elevated serum C-reactive protein (CRP) levels were associated with coronary heart disease (CHD) events." (PMID 24453409, 2013). "Genetic studies based on the “Mendelian randomisation” approach have assessed the causal relevance of CRP itself to coronary heart disease." (PMID 23285251, 2012). "The goal of this prospective study was to assess the effect of cardiac rehabilitation on high sensitive CRP as a marker of increased risk of coronary artery disease." (PMID 22737555, 2012). "High-sensitivity C-reactive protein (hs-CRP) assay is of great clinical importance in predicting risks associated with coronary heart disease." (PMID 22309411, 2012). "Similar to the findings of the current study, these investigators reported that a comorbidity score (including ischemic heart disease) was among those factors that were significantly associated with variations in the CRP." (PMID 22121485, 2012). "Epidemiological evidence suggests that fibrinogen and CRP are associated with coronary heart disease risk." (PMID 21029470, 2010). "Recently, polymorphisms in the gene for HNF1α have been linked to the levels of C-reactive protein and coronary artery disease." (PMID 21062467, 2010). "Some biomarkers such as myeloperoxidase and high-sensitivity C-reactive protein in an apparently healthy population predicts risk of coronary disease and allows clinicians to initiate early preventative treatment." (PMID 20529285, 2010). "The researchers identified 83 studies that investigated the association between CRP levels measured in people with coronary artery disease and subsequent cardiovascular events." (PMID 20532236, 2010). "Recently, polymorphisms in the HNF1A gene (also known asTCF1, MIM 142410) have been linked to the levels of C-reactive protein and coronary artery disease." (PMID 21062467, 2010). "Although all studies included patients with stable coronary disease, the magnitude of association between CRP and outcomes was greater among studies in which the percentage of stable patients was not stated." (PMID 20532236, 2010). "The inverse association between adiponectin and CRP (R = -0.35) in our study is consistent with what has been reported in patients with coronary artery disease." (PMID 19570238, 2009).
coronary artery disease (continued). "rs3091244 is a tri-allelic SNP located in the promotor region of the CRP gene that has been associated with elevated baseline CRP levels, and increased risk of coronary artery disease (CAD) in ambulatory patients." (PMID 19426506, 2009). "Classical cardiac markers usually considered as strong predictors among patients with coronary disease, are Troponin T (TnT) and C-reactive Protein (CRP), both related to increased risk of recurrent ischemic events and cardiovascular death." (PMID 19690642, 2007). "Elevated levels of highly sensitive C-reactive protein (hs-CRP) have been related to increased risk of cardiovascular disease, myocardial infarction, and coronary artery disease (CAD) deaths among individuals with angina pectoris." (PMID 17374166, 2007). "Individuals infected with multiple pathogens such as HSV-1, HSV-2, CMV and H. pylori have high C-reactive protein levels (markers of inflammation) and the greatest relative risk for coronary artery disease." (PMID 17140429, 2006). "Using the MDR method, we showed that the combination of CETP TaqIB polymorphism and the presence of albuminuria, an elevated CRP, renal dysfunction or ischemic heart disease are the best models for predicting AF in this nested case-control study." (PMID 16623947, 2006). "On the other hand, an additive interaction was observed between the CETP TaqIB polymorphism and elevated C-reactive protein, presence of renal dysfunction or ischemic heart disease." (PMID 16623947, 2006). "For example, CRP is observationally associated with coronary heart disease (CHD), but prior to robust MR studies it was unknown whether this association was causal." (PMID 40547872, 2025). "Moreover, circulating levels of IL-6 and CRP have been linked to elevated endothelial microparticles in coronary heart disease." (PMID 41155389, 2025). "In the AtheroGene study, including 3423 patients with angiographically documented coronary heart disease, higher concentrations of TR were strongly associated with increased risk of myocardial infarction or cardiovascular death independently of CRP or hemoglobin." (PMID 40503438, 2025). "cTnT was significantly positively correlated with the following risk factors (Coronary heart disease: ρ = 0.302, p < 0.01; Insular cortical lesions: ρ = 0.329, p < 0.01; Peak NT-proBNP: ρ = 0.538, p < 0.01; C-reactive protein: ρ = 0.436, p < 0.01; NIHSS score: ρ = 0.378, p < 0.01)." (PMID 41541883, 2025). "Finally, we apply the proposed method to the Atherosclerosis Risk in Communities study to estimate the marginal causal effect of high-sensitivity C-reactive protein level on coronary heart disease-free survival." (PMID 40820181, 2025). "Notably, using the same thresholds we adopted in our analyses, elevated CRP levels have been shown nearly to double the risk of coronary heart disease at 10‐year follow‐up." (PMID 39526963, 2025). "Previous studies have already emphasized that fruit and vegetable consumption may reduce the risk of coronary heart disease in part through the lowering of C-reactive protein (CRP)." (PMID 39337053, 2024). "In addition, in the general population, CRP, is also considered to be a marker of inflammation, and a powerful risk factor for ischemic heart disease and peripheral atherosclerosis." (PMID 39427162, 2024). "Furthermore, even a slight yet persistent increase in CRP or high-sensitivity CRP (hs-CRP) has been correlated with the presence of coronary artery disease and a heightened risk of future cardiovascular events among apparently healthy individuals." (PMID 38667035, 2024). "Moreover, increased CRP levels have been linked with atherosclerotic disease, congestive heart failure, and ischemic heart disease, suggesting that it is not only a biomarker but also plays an active role in the pathophysiology of cardiovascular diseases." (PMID 38627621, 2024). "Also, high CRP levels are associated with increased coronary heart disease and overall mortality as reported by95." (PMID 38316807, 2024).
coronary artery disease (continued). "We investigated whether plasma concentrations of CRP and glucose were causally associated and their associations with risk of ischemic heart disease (IHD) and CVD death." (PMID 38730445, 2024). "The American Heart Association recommends that elevated CRP levels may be a predictor of coronary heart disease and unsuspected serious non‐vascular disease in adults." (PMID 37310092, 2023). "This stratification approach has been used to show that the effect of smoking on risk of bladder cancer is greater for those with low bodyweight, and that the effect of interleukin-6 receptor inhibition on coronary heart disease risk is greater for those with high levels of C-reactive protein." (PMID 36736292, 2023). "Notably, IL1RA colocalised with five cardiometabolic traits (CRP, low density lipoprotein cholesterol, total cholesterol, triglycerides, and glucose), and coronary artery disease risk colocalised with MCSF and TRAIL." (PMID 36936266, 2023). "Previous studies reported that sSema4D and hs-CRP levels may be independent risk factors for coronary heart disease." (PMID 37138227, 2023). "Older data suggest that, generally, CRP, possibly with different cut-offs, should be used as a marker of risk and as a guide to manage patients hospitalized for acute coronary syndromes and in outpatients with ischemic heart disease." (PMID 37873776, 2023). "Indeed, the inflammatory marker high sensitivity C-reactive protein is already used to screen for coronary disease predisposed by chronic low-level inflammation." (PMID 36810528, 2023). "Sleep restriction in adult males who sleep normally leads to increased sympathetic, norepinephrine, and pro-inflammatory cytokines (interleukin-1, interleukin-6, and C-reactive protein) activity, which are independently associated with coronary heart disease and death." (PMID 37082612, 2023). "As recommended by the American Heart Association24, patients at intermediate or high risk of coronary heart disease may benefit from the measurement of hs-CRP and future cardiovascular risk." (PMID 37744945, 2023). "The evidence from meta-analyses of long-term prospective studies comprising 160,309 people showed that increased circulating levels of inflammatory biomarker C-reactive protein were linked to increased risks of coronary heart disease, ischaemic stroke, and mortality." (PMID 35563697, 2022). "Similarly, plasma sortilin has demonstrated significant association with hs-CRP, which has been found to be formed in vascular smooth muscle cells, in patients with coronary artery disease whose platelets were suppressed by aspirin treatment." (PMID 35732620, 2022). "Moreover, polymorphisms in IL-38 are associated with coronary artery disease and C-reactive protein (CRP) concentrations in humans." (PMID 35634320, 2022). "Cement workers and cleaners recorded the highest risk of coronary heart disease (CRP ≥ 3.0 mg/L)." (PMID 36138426, 2022). "Nine biomarkers outcomes were collected at 46 years of age: body mass index (BMI), blood pressure, total and high-density cholesterol, triglycerides, glycated haemoglobin, C-reactive protein (CRP), insulin-like growth factor 1 and we computed the 10-year risk for coronary heart disease." (PMID 34583963, 2022). "In addition, alcohol consumption, LDL-C, coronary artery disease, arthritis, and steroid use are also associated with elevated CRP." (PMID 36418968, 2022). "However, inflammation markers such as us-CRP (high serum sensitivity C-reactive protein) can also be considered important indicators to estimate the severity and risk of coronary artery disease." (PMID 35237168, 2022). "Moreover, increased risk of coronary heart disease in RA is associated with elevated CRP and erythrocyte sedimentation rate, the presence of RF and/or ACPA, as well as with highly active or severe RA." (PMID 36052337, 2022).
coronary artery disease (continued). "Overall, 12 distinct phenotypes presented significant associations at a P < 0.01, of which four (Crohn’s disease, ischemic heart disease, systolic and diastolic blood pressure) presented significant associations (P < 0.01) when the instruments were restricted to CRP gene locus." (PMID 32978716, 2021). "The risk of CVDs, including coronary heart diseases and peripheral arterial diseases, can be predicted and characterized by cardiovascular biomarkers such as C-reactive protein (CRP) and vascular endothelial growth factor, which are related to systemic inflammation and endothelial dysfunction." (PMID 34803716, 2021). "C-reactive protein levels of over 200 were associated with increased macrophageal infiltration of alveoli (p = 0.045), reduced myxoid edema (p = 0.016) and were more common in patients with ischemic heart disease (p = 0.009)." (PMID 34421396, 2021). "In prospective cohort studies, also the length of follow-up with respect to age at baseline amongst study participants, as in the risk of coronary heart disease (CHD) associated with high levels of C-reactive protein, and possible competing events affect the interpretation of study results." (PMID 34159863, 2021). "In addition, the variant (rs7529229) of the IL-6 receptor, which increases the level of circulating IL-6 and lowers the concentration of C-reactive protein and fibrinogen, reduced the risk of coronary heart disease events." (PMID 34071276, 2021). "In univariate analysis the CRP level was significantly associated with coronary heart disease (p < 0.0001), histology (squamous cell carcinoma; p = 0.013), tumor size (T1a; p = 0.018 and T2a; p = 0.002), tumor stage (p = 0.002), and vascular invasion (p = 0.017)." (PMID 31936329, 2020). "In a study of nearly 1000 participants with coronary artery disease, elevated CRP levels coupled with CMV seropositivity were associated with mortality, whereas neither elevated CRP levels without CMV nor CMV seropositivity without elevated CRP showed such an association." (PMID 33089035, 2020). "In 2003, the American Heart Association suggested that CRP levels be used in screening healthy adults for increased risk of coronary heart disease (levels above 3 mg/L) and for the detection of unsuspected and severe non-vascular diseases (levels above 10 mg/L)." (PMID 33239071, 2020). "The overall certainty of the evidence was high for LDL cholesterol, total cholesterol, non-HDL cholesterol, triglycerides, apolipoprotein B and body weight and moderate for HDL cholesterol, systolic blood pressure, diastolic blood pressure, CRP and estimated 10-year coronary heart disease risk." (PMID 31540227, 2019). "Whether high sensitivity C-reactive protein (hs-CRP) has a causal effect on coronary heart disease (CHD) is unclear." (PMID 31694563, 2019). "ACS is associated with inflammatory and non-inflammatory risk factors; high blood levels of C-reactive protein (CRP) may be linked with risk of coronary artery disease and having a heart attack." (PMID 29337850, 2018). "A Mendelian randomization study of over 28,000 cases and 100,000 controls found that a lack of concordance between the effect of the CRP genotypes on the risk of coronary heart diseases and CRP levels argued against a causal association of CRP with coronary heart disease." (PMID 29951057, 2018). "A large meta-analysis of individual participant data reported that 1-standard deviation (SD) higher loge CRP concentration was associated with 37% (95% CI 27–48%) higher risk of coronary heart disease and 27% (15–40%) higher risk of ischemic stroke, after adjusting for classic vascular risk factors." (PMID 28477314, 2017). "High-sensitivity C-reactive protein (hs-CRP) is independently associated with cardiovascular events in coronary artery disease (CAD) patients and reducing the hs-CRP level may further benefit this population." (PMID 29234038, 2017).